C4BPB (complement component 4 binding protein beta)
Description:
Controls the classical pathway of complement activation. It binds as a cofactor to C3b/C4b inactivator (C3bINA), which then hydrolyzes the complement fragment C4b. It also accelerates the degradation of the C4bC2a complex (C3 convertase) by dissociating the complement fragment C2a. It also interacts with anticoagulant protein S and with serum amyloid P component. The beta chain binds protein S.
Synonyms: C4BP
Tractability: Antibody: its Gene Ontology location is reachable by antibodies, with high confidence; UniProt places it where antibodies can reach, with medium confidence; UniProt predicts a signal peptide or a membrane-spanning region. PROTAC: ubiquitination databases record sites on it; its protein half-life has been measured.
Gene: Protein-coding gene on chromosome 1 (207,088,802 to 207,100,001, forward strand). Ensembl gene ENSG00000123843.
Subcellular location: Secreted
Subcellular location (Human Protein Atlas): Golgi apparatus; Predicted to be secreted
Pathways (Reactome):
Disease: Dengue virus activates/modulates innate and adaptive immune responses
Immune System: Regulation of Complement cascade
Gene Ontology:
Molecular function: protein binding
Biological process: negative regulation of complement activation, classical pathway; positive regulation of protein catabolic process; regulation of opsonization; response to symbiotic bacterium; blood coagulation
Cellular component: extracellular region; plasma membrane
Genetic constraint (gnomAD): Loss-of-function variants: 15 observed, 20.14 expected, observed/expected ratio (o/e) 0.74, 90% interval 0.5 to 1.15. The upper end of that interval is the gene's LOEUF score, 1.15, which puts it in group 5 of 6, group 1 being the genes least tolerant of losing a copy. Missense variants: 232 observed, 263.34 expected, observed/expected ratio (o/e) 0.88, 90% interval 0.79 to 0.98. Synonymous variants: 104 observed, 91.63 expected, observed/expected ratio (o/e) 1.13, 90% interval 0.97 to 1.34.
Homologues: Orthologues: chimpanzee C4BPB (99% identical), macaque C4BPB (92% identical), pig C4BPB (70% identical), dog C4BPB (69% identical), guinea pig C4BPB (68% identical), rat C4bpb (66% identical). Paralogues in human: CSMD3 (24% identical), CR2 (23% identical), CSMD1 (23% identical), CSMD2 (22% identical), CFH (21% identical), SVEP1 (21% identical), CR1 (21% identical), C4BPA (21% identical), F13B (20% identical), APOH (19% identical), SEZ6L2 (19% identical), SUSD4 (19% identical), and 27 more.
Diseases named in the same sentence as C4BPB in open-access papers:
C4BPB is named in the same sentence as 23 diseases in open-access papers, as found by Europe PMC text mining. Sharing a sentence is not in itself a finding about the gene and the disease. The quoted sentences say what the papers report.
COVID-19 (3 papers, 2021 to 2022). A disease caused by infection with severe acute respiratory syndrome coronavirus 2. "LGALS3BP abundance in COVID-19 patients closely correlated with proteins and regulators of the complement cascade (C6, C9, C4BPA, and C4BPB)." (PMID 34099652, 2021).
lung carcinoma (2 papers, 2019 to 2021). "With the exception of the C4BPB mRNA, other complement components were significantly elevated at both mRNA and protein levels in QSG-7701 hepatocytes co-cultured with lung cancer cells compared to QSG-7701 hepatocytes co-cultured with HBE cells." (PMID 30841875, 2019).
psychotic disorder (2 papers, 2021). An abnormal condition of the mind that involves a loss of contact with reality. "Decreased C4b-binding protein alpha chain (C4BPA) and C4b-binding protein beta chain (C4BPB) levels were found in children preceding the onset of psychotic disorder." (PMID 33670154, 2021).
Allergy (1 paper, 2020). An allergy is an immune response or reaction to substances that are usually not harmful. "Based on their association with allergy and the protein fold change (more than 1.1 or less than 0.9) between ATI responders and non-responders, four potential genes (MUC5B, LBP, C4BPB, LTA4H) were identified as potential biomarkers that indicate an effective AIT." (PMID 33329520, 2020).
Headache (1 paper, 2025). Cephalgia, or pain sensed in various parts of the head, not confined to the area of distribution of any nerve. "Among these associations, 108 proteins were associated with headache, of which C4BPB (odds ratio [OR] = 1.59, P = 1.67 × 10−39), IL18R1 (OR = 1.55, P = 7.36 × 10−25), and CDHR5 (OR = 1.46, P = 6.31 × 10−23) had the strongest associations." (PMID 40048323, 2025).
inflammatory bowel disease (1 paper, 2024). A spectrum of small and large bowel inflammatory diseases of unknown etiology. "C4BPA expression was found to be increased in patients with irritable bowel syndrome, while C4BPB expression was found to be increased in patients with inflammatory bowel disease." (PMID 38671889, 2024).
Insulin resistance (1 paper, 2019). Increased resistance towards insulin, that is, diminished effectiveness of insulin in reducing blood glucose levels. "protein C receptor, endothelial (EPCR) (PROCR), C1R, CFI, PLAT, C4BPB, and CFB are novel biomarkers for the development of insulin resistance." (PMID 30678306, 2019).
pneumonia (1 paper, 2017). An acute, acute and chronic, or chronic inflammation focally or diffusely affecting the lung parenchyma, caused by an infection in one or both of the lungs (by bacteria, viruses, fungi, or mycoplasma.). "In the present study, we established decision tree diagnostic models consisting of SAA, PROZ, and C4BPB to discriminate patients with TB from healthy controls, patients with pneumonia or COPD, and treated TB cases." (PMID 28278182, 2017). "Receiver operating characteristic curve analysis revealed that the area under the curve value of the diagnostic model combining SAA, PROZ, and C4BPB to discriminate the TB group from the healthy control, pneumonia, COPD, and cured TB groups was 0.972, 0.928, 0.957, and 0.969, respectively." (PMID 28278182, 2017). "Receiver operating characteristics of SAA, PROZ, and C4BPB in distinguishing patients with TB from healthy controls, patients with pneumonia or COPD, and treated TB cases individually and as a panel." (PMID 28278182, 2017). "The three new candidate biomarkers SAA, PROZ, and C4BPB were validated by ELISA in 136 patients with TB, 66 healthy controls, 72 patients with pneumonia, and 72 patients with COPD." (PMID 28278182, 2017). "However, few studies are available regarding the serum concentration of PROZ and C4BPB in patients with pneumonia or COPD." (PMID 28278182, 2017). "ELISA analysis revealed that serum C4BPB, SAA, and PROZ in patients with TB differed significantly from healthy controls, patients with pneumonia or COPD, and treated TB cases." (PMID 28278182, 2017).
pulmonary TB (1 paper, 2017). "Therefore, SAA, PROZ, and C4BPB may be suitable as new potential diagnostic biomarkers for pulmonary TB." (PMID 28278182, 2017).
schizophrenia (1 paper, 2015). A major psychotic disorder characterized by abnormalities in the perception or expression of reality. "We have examined the association of schizophrenia with the gene encoding C4-binding protein (C4BPB/C4BPA), a potent circulating soluble inhibitor of the classical and lectin pathways of complement." (PMID 26305563, 2015). "However, our results did not support the involvement of C4BPB/C4BPA in schizophrenia." (PMID 26305563, 2015).
Sepsis (1 paper, 2017). Sepsis is defined as life-threatening organ dysfunction caused by a dysregulated host response to infection. "Notably, the plasma concentration of protein C4BPB has been found to be increased in patients with sepsis and other patients with an acute phase response." (PMID 28278182, 2017).
viral infection (1 paper, 2023). "Notably, four markers (C4BPB, TCN2, SMD9L, and C1QA) displayed an AUC exceeding 0.8, with a combined AUC of 0.95, suggesting their potential to serve as early markers for viral infection and severe disease." (PMID 37942334, 2023).
infection (4 papers, 2019 to 2023). The state of being infected such as from the introduction of a foreign agent such as serum, vaccine, antigenic substance or organism. "Among the markers, C4BPB, which exhibited the best performance, was exclusively expressed in AT1/AT2 cells, indicating early infection and tissue damage." (PMID 37942334, 2023). "Of the top 20 contributing proteins for each infection identified by machine learning, 6 were found to be common to both LD and WNV (APOD, C4BPB, C7, HP, ITIH3, PGLYRP2), but with varying degrees of importance in each disease." (PMID 36569838, 2022). "During acute infection (7 dpi), PRRSV significantly represses the expression of complement regulatory components (CD55 and C4BPB) in lung tissue." (PMID 32731586, 2020).
cancer (2 papers, 2022 to 2025). A tumor composed of atypical neoplastic, often pleomorphic cells that invade other tissues. "While the roles of C4BPB, HLA-C, and SERPINB1 in cancer immunobiology have been increasingly recognized, direct evidence of their function in PDAC remains limited." (PMID 41007761, 2025). "These candidates have rather decreasing (HV404, XPP1, MANBA, TENX)or increasing (LEG1, C4BPB) trends in a cancer agnostic manner, withthe exception of GTR1, which strongly increases in the late-stagebreast cancer while decreasing in the other types." (PMID 35605973, 2022).
C4BPB also shares sentences with these, for which no sentence is quoted: rheumatoid arthritis (2 papers); Cirrhosis (1); endometrial cancer (1); Hepatic fibrosis (1); Hepatic steatosis (1); irritable bowel syndrome (1); tumor (1); ulcerative colitis (1); Venous thrombosis (1).